OR8B3 (olfactory receptor family 8 subfamily B member 3)
Description:
Odorant receptor.
Synonyms: OR11-311
Tractability: Antibody: its Gene Ontology location is reachable by antibodies, with high confidence; UniProt places it where antibodies can reach, with medium confidence; UniProt predicts a signal peptide or a membrane-spanning region.
Gene: Protein-coding gene on chromosome 11 (124,395,534 to 124,399,024, reverse strand). Ensembl gene ENSG00000284609.
Subcellular location: Cell membrane
Pathways (Reactome):
Sensory Perception: Expression and translocation of olfactory receptors; Olfactory Signaling Pathway
Gene Ontology:
Molecular function: olfactory receptor activity; G protein-coupled receptor activity
Biological process: G protein-coupled receptor signaling pathway; sensory perception of smell; detection of chemical stimulus involved in sensory perception of smell
Cellular component: plasma membrane; membrane
Genetic constraint (gnomAD): Loss-of-function variants: 0 observed, 0.0766 expected, observed/expected ratio (o/e) 0, 90% interval 0 to 1.89. That is too few expected variants to judge how well the gene tolerates losing a copy. Missense variants: 258 observed, 310.56 expected, observed/expected ratio (o/e) 0.83, 90% interval 0.75 to 0.92. Synonymous variants: 93 observed, 109.3 expected, observed/expected ratio (o/e) 0.85, 90% interval 0.72 to 1.01.
Homologues: Orthologues: chimpanzee OR8B3 (97% identical), dog OR8B3 (90% identical), rat Or8b3 (84% identical), rat Or8b3c (84% identical), mouse Or8b3 (83% identical), mouse Or8b3b (80% identical). Paralogues in human: OR8B2 (98% identical), OR8B8 (71% identical), OR8B12 (68% identical), OR8B4 (67% identical), OR8G1 (65% identical), OR8G5 (64% identical), OR8A1 (63% identical), OR8G3 (62% identical), OR8G2P (60% identical), OR8D2 (59% identical), OR8D1 (58% identical), OR8D4 (58% identical), and 84 more.